NOS2 (nitric oxide synthase 2)
Diseases named in the same sentence as NOS2 in open-access papers (continued):
Sharing a sentence is not in itself a finding about the gene and the disease.
tumor (continued). "IFN-γ produced from stroma-restricted TEff cells is crucial for the induction of tumor NOS2/COX2 expression in TNBC, where the resultant NO/PGE2 production inhibits B cell activation and TEff cell antitumor function, respectively." (PMID 40663402, 2025). "The spatial distribution of PDL1Tumor expression did not change significantly across analyzed regions, while COX2 expression was primarily localized near NOS2+ edges and tumor satellite regions." (PMID 40663402, 2025). "We also analyzed the expression of M1 markers (IL‐1β, Nos2, TNFα) and M2 markers (Arg‐1, CD206, IL‐10) in tumor‐associated macrophages." (PMID 39791593, 2025). "To further explore the immune dynamics associated with the NOS2/ARG axis and tumor progression, we examined the ratios of circulating immune cells." (PMID 41573553, 2025). "To further explore the immune dynamics associated with the NOS2/ARG1 axis and tumor behavior we analyzed the proportions of circulating immune cells." (PMID 41573553, 2025). "These 2 distinct profiles of tumors from deceased and living patients demonstrate the strong predictive value of tumor NOS2/COX2 expression with respect to an effective immune response and improved survival." (PMID 40663402, 2025). "The concordance between the computational prioritization of NOS2 (iNOS2) and its experimentally confirmed downregulation across immune and tumor supports NOS2 (iNOS2) as a key functional effector of these oils." (PMID 41598205, 2025). "To analyze the neutrophil properties, we used the following frequently mentioned profiles: pro-tumor anti-inflammatory profile (Mmp9, Vegfa, Arg1, Nos2, Ccl17, Il10) and anti-tumor pro-inflammatory profile (Icam1, Tnfa)." (PMID 40001601, 2025). "Previous studies have established the NOS2/ARG1 axis as a critical modulator of tumor progression and metastasis." (PMID 41573553, 2025). "This dichotomy represents a classic negative feedback mechanism, where IFN-γ from activated TEff cells increases tumor NOS2 and COX2 expression, dampening the Th1 antitumor response." (PMID 40663402, 2025). "M1-polarized macrophages, characterized by NOS2 expression, promote tumor suppression through pro-inflammatory activity, whereas M2-like macrophages, which often express ARG1, contribute to immune suppression, matrix remodeling, and therapeutic resistance." (PMID 41573553, 2025). "The specific spatial orientation of TEff/NOS2/COX2 provides a key determinant of outcome that shapes the tumor immune microenvironment." (PMID 40663402, 2025). "In contrast, low NOS2/COX2-expressing tumors from alive patients exhibited elevated CD8+ T cells with abundant infiltration from the tumor-stroma margin deep into the tumor core." (PMID 40663402, 2025). "Other tumor ISGs regulated by type I IFNs such as NOS2 and CD38 can also have immune-suppressive effects and have been implicated to promote resistance to PD-1 pathway blockade." (PMID 39663510, 2025). "To test this, we treated mice engrafted with WT or IFNγRKO tumours with the NOS2 (INOS) inhibitor L-NAME." (PMID 39746898, 2025). "In contrast, M1-biased macrophages combat tumor growth and bacterial infections by expressing inducible nitric oxide synthase 2 (NOS2), which catalyzes the production of nitric oxide (NO)." (PMID 40430260, 2025). "The qPCR analysis of total mRNA from tumor tissues revealed significant upregulation of M1 markers Nos2, Il1b, and Il6, along with marked downregulation of M2 markers Mcr1, Arg1, and Il10." (PMID 39908200, 2025). "The resistance is accompanied by increased NOS2 and •NO production, which promote tumour growth and reduce the effect of anti-KRAS drugs." (PMID 40567499, 2025).
tumor (continued). "With these carboxylic acid-modified derivatives in hand, we investigated their impact at 10 μM on ARG1 and NOS2 mRNA expression in RAW 264.7 cells pre-stimulated with IL-4/IL-13 to evaluate the effects on the pro-tumor phenotype of macrophages." (PMID 40430260, 2025). "Tumor-derived exosomes (TDE) stimulate elevated nitric oxide synthase 2 (NOS2), thereby inhibiting mitochondrial oxidative phosphorylation, and promoting conversion of pyruvate to lactate." (PMID 40786181, 2025). "To further explore survival relationships between tumor NOS2 and COX2 expression relative to T cells, PD1, PDL1, and FOXP3 immunosuppressive markers, we evaluated the ratios of the percentage of cells expressing each marker to tumor NOS2 or COX2." (PMID 40663402, 2025). "IFN-γ and cytokines are essential for tumor eradication, while IFN-γ–induced NOS2/COX2 induction is linked to poor prognoses." (PMID 40663402, 2025). "INOS-induced tumour control was less effective in WT tumours, consistent with the fact that fewer NOS2+ macrophages are present in WT compared to IFNγRKO tumours." (PMID 39746898, 2025). "In contrast, patients with stroma- or margin-restricted CD8+ TEff cells and elevated tumor NOS2/COX2 are associated with abated CD8+ TEff penetration and increased tumor invasion and metastasis." (PMID 40663402, 2025). "Immune evasion was evident through upregulation of NFKB1, IFNAR1, TLR4, IL1A/B/R1, and NOS2, facilitating tumour escape from immune surveillance." (PMID 41007296, 2025). "Quantitative analysis of tumor NOS2 and COX2 expressions revealed multiple levels of signal intensity for NOS2, but not COX2." (PMID 39356141, 2024). "Both grain-treated groups had attenuated levels of the marker of M1 macrophages Nos2 in the tumor tissue." (PMID 38891915, 2024). "In our previous study, we demonstrated that stromal-restricted CD8+ T cells and limited lymphoid aggregates were closely positioned but orthogonal to tumor regions exhibiting high levels of NOS2 and COX2." (PMID 38892290, 2024). "Tumor NOS2 density was evaluated at the tumor edge where tumor satellite regions indicative of invasive tumor cells contained significantly higher NOS2 expression, whereas NOS2 was lowest in lymphoid aggregates and the tumor core." (PMID 39356141, 2024). "In contrast, the NOS2−/CD8− phenotypes were observed in immune dessert regions, whereas the NOS2+ phenotypes in deceased patient tumors had stroma-restricted CD8+ T cells, and high tumor NOS2 expression was observed at the tumor margins." (PMID 39356141, 2024). "Comparing murine macrophages and tumor cells, a temporal distinction emerges, where the maximum NOS2 in macrophages and murine tumor cells occurs within 8 h to 24 h." (PMID 38892290, 2024). "Further analysis of tumor cross‐sections with enriched neutrophil infiltrations revealed the upregulation of neutrophil‐related genes such as S100a9, Serpine1, Mt2, Nos2, Mt1, IL33, Adm, and Ero1l." (PMID 39113226, 2024). "NOS2 was identified at the tumor-stromal interface, while COX2 was present in the vicinity of immune desert regions closer to the tumor core." (PMID 38892290, 2024). "In contrast, NOS2/COX2 blockade augments cytolytic T cells, mature B cells, and neutrophils associated with resistance to 4T1 tumor rechallenge in 4T1 tumor-bearing mice." (PMID 39356141, 2024). "This NOS2/COX2 spatial configuration in specified areas of the tumor indicated an increased metastatic potential." (PMID 38892290, 2024). "The S-UMAP analysis revealed highly significant correlations between EpCAM in lymphoid restricted regions, where elevated IFNγ and NOS2 were expressed, either at the tumor edge or in tumor satellites areas." (PMID 39356141, 2024). "We recently demonstrated significant correlations between tumor NOS2 and COX2 expression and both stroma-restricted CD8+ T effector cells and secreted IFNγ in these tumors." (PMID 39356141, 2024).
tumor (continued). "Previous studies have demonstrated the requirement of IFNγ and IL1/TNF cytokines for tumor NOS2/COX2 expression, in which correlations between tumor NOS2 and CD8 expressions were observed at the tumor stroma interface." (PMID 39356141, 2024). "TAMs undergoing different classic (M1) or alternative (M2) phenotypic polarization express the specific M1 marker nitric oxide synthase-2 (NOS2) or the M2 markers CD206 which are believed to hold tumor-preventing or -promoting activities." (PMID 38956496, 2024). "We selected four human cancer cell lines derived from aggressive tumor types that are known to express NOS2 and synthesize NO in vivo (2 triple negative breast (TNBC), 1 prostate, 1 brain)." (PMID 38645113, 2024). "Both grain diets produced a reduction in the spleen weight index, along with a decrease in the mRNA levels of the M1 macrophage marker Nos2 in the tumor and a decrease in the G-CSF serum levels, indicating an anti-inflammatory effect of the grain diets." (PMID 38891915, 2024). "In murine systems, the requirement of IFNγ for tumor Nos2 expression has been shown, which was amplified by other cytokines including IL1β and TNFα." (PMID 39356141, 2024). "The relationship between IDO1 and marker genes of tumor-associated macrophages (TAMs; CCL5, CD68, and IL10), M1 (IRF5, NOS2, and PTGS2), and M2 (CD163, VSIG4, and MS4A4A) macrophages was analyzed." (PMID 39351094, 2024). "We report that NRP2-expressing cells serve as a hub for NO production, by enhancing NOS2 transcription via Gli1, which creates local fields within the tumor that can protect the cells from radiation." (PMID 39352757, 2024). "The discussion above emphasizes that small, concentrated regions of NOS2-expressing tumor cells, compared to the entire tumor, can significantly impact survival." (PMID 38892290, 2024). "The spatial localization of tumor NOS2/COX2 expression versus CD8+ T cells shows a different pattern within the defined regions." (PMID 39356141, 2024). "Given the functions of these cells in anti-tumor immune response and their variation in HB samples with high-NOS2 expression, it became apparent that high-NOS2 expression indicated an unfavorable anti-tumor immune process." (PMID 37795447, 2023). "Murine tumor cells displayed significantly higher NOS2 activity in response to IFNγ or LPS, suggesting a key distinction between tumor cells and macrophages." (PMID 37169743, 2023). "CCL2, ARG1, ARG2, NOS2, and CCL5 are well-known N2-associated cytokines that promote tumor growth, invasion, and immune suppression." (PMID 37174093, 2023). "NOS2/COX2 fluorescent intensities of the entire tumor quantified from these thresholds were consistent with the original IHC Pathologist scored NOS2/COX2 expression levels previously reported." (PMID 37169743, 2023). "Elevated CD8+ T cells and other lymphoid cells that are restricted to tumor stroma or margins can result in situations that promote higher NOS2 and COX2." (PMID 37169743, 2023). "In turn, high levels of NO, a product of NOS2 activity, can stimulate cell growth, dilate tumour vessels to maintain blood supply to the tumour, and thus is crucial for tumour angiogenesis." (PMID 37660159, 2023). "In further support of a shift toward M1 activity, fulvestrant co-treatment with RT significantly elevated Nos2 transcripts, a marker for M1 macrophages, in the bulk tumor, compared to tumors treated with RT alone." (PMID 37312163, 2023). "Here we demonstrate that high NOS2 cellular niches can be formed at the tumor margin and proximal to stroma-restricted CD8+ T cells." (PMID 37169743, 2023).
tumor (continued). "Levels of TGF-β, which has anti-tumor effects in early-stage cancer but tumor–promoting effects in late-stage cancer, IL-10, and nitric oxide synthase 2 (NOS2) increase as tumors progress." (PMID 37108802, 2023). "NO produced by NOS2-expressing myeloid cells acts together with CD8+ T-cells to eliminate tumour cells." (PMID 37446252, 2023). "Our study revealed that FRGs have potential prognostic value in CRC patients and that NOS2 suppresses tumor progression, providing a novel therapeutic target for CRC treatment based on ferroptosis." (PMID 37346068, 2023). "Viable tumor and stroma regions were annotated by a Veterinary Pathologist on H&E images (QuPath) and fused with NOS2/COX2 fluorescent expression using HALO software." (PMID 37169743, 2023). "Herein, we further explored the influence of tumor cell NOS2/COX2 expression on altered cellular morphology." (PMID 37169743, 2023). "LCN2/NGAL prevents bacterial development by securing iron-containing siderophores, while NOS2 produces nitric oxide, a reactive free radical that is a biological moderator in antibacterial, neurotransmission, and anti-tumor effects." (PMID 37259466, 2023). "IDO1, NOX1, CXCL3, IL1RL2 and NOS2 were upregulated, as their expression levels were lower in the healthy group and higher in the tumor group." (PMID 36911403, 2023). "Significant upregulation of expression is found in genes associated with tumor cell invasion such TGFβ1, ROAR, DAB2, BMP6, NOS2, PLXN2, and CADPS, whereas TCF4 was significantly downregulated in AHCY deficient cells." (PMID 38003292, 2023). "First, NOS-2 expression and NO overproduction contribute to the formation of an inflammatory cancer microenvironment, which promotes tumor cell proliferation." (PMID 36900358, 2023). "High expression and clustering of NOS2-expressing tumor cells occurred at the tumor/stroma interface in the presence of stroma-restricted CD8+ T cells." (PMID 37169743, 2023). "We found that many myeloid cell markers were highly expressed in hybrid tumor cells, including Ly6e, Ly6c2, Ccl2, Nos2, Cxcl1, and Cxcl2." (PMID 37138326, 2023). "Some key enzymes of neutrophils, such as Arg1 and Nos2, are directly or indirectly inhibited to reduce their tumor-promoting effects." (PMID 37496019, 2023). "NOS2 is positively correlated with tumor proliferation and microvascular formation, negatively correlated with cell apoptosis, and significantly correlated with a poor prognosis in HCC." (PMID 37958916, 2023). "In this study, we investigated the role of endogenous NO production in CD8+ T cells and use Nos2 deletion models specific to T cells to determine the role of NO synthesis during tumor immunity." (PMID 36574610, 2023). "When stratifying for tumor vs stroma, NOS2/COX2 tumor expression with strong/moderate signal intensity was significantly elevated in NOS2/COX2 high-expressing tumors." (PMID 37169743, 2023). "Nonetheless, NO levels are higher where NOS2-expressing cells are concentrated at a much higher density, such as in localized foci inside the tumor." (PMID 37169743, 2023). "The results showed that the number of tumor-infiltrating Nos2+ M1-biased macrophages increased whereas the number of Arg1+ M2-biased macrophages decreased." (PMID 36798830, 2023). "In contrast, NOS2hi/COX2hi tumors exhibited numerous, spatially distinct, high-expressing NOS2 and COX2 foci, with NOS2 clusters at the tumor-stroma interface." (PMID 37169743, 2023). "Transfer with KA/KA and KA/KA;Nos2-/- bone marrow (BM) to irradiated wild-type (WT), KA/KA, or KA/KA;Nos2-/- mice demonstrated that iNOS in tumor cells and macrophages contributes to lung SCC development." (PMID 37686574, 2023). "NOS2 was one of the most significantly affected FRGs and was highly expressed in malignant tissue, but it inhibited tumor growth and induced tumor cell death in vitro and in vivo, possibly by repressing the NF-κB pathway." (PMID 37346068, 2023).
tumor (continued). "A powerful relationship between tumor NOS2/COX2 expression and distinct CD8+ T cell phenotypes was observed at 5 years post-diagnosis." (PMID 38187532, 2023). "Apart from macrophages, the Nos2 gene is expressed in multiple cell types including dendritic cells, NK cells and primary tumor cells." (PMID 37842051, 2023). "NQO1, SLC1A4, and NOS2 were identified as potential genes in HB and found to be significantly upregulated in tumor samples." (PMID 37795447, 2023). "On the other hand, Nos2 and Il1a, indicative of M1 macrophages, were also upregulated, suggesting a mix of macrophage subtypes within the primary tumor in the wake of irradiation." (PMID 37345658, 2023). "Genetic deletion of Nos2 expression in murine T cells altered effector differentiation, reduced tumor infiltration, and inhibited recall responses and adoptive cell transfer function." (PMID 36574610, 2023). "TNF-α secretion in the tumor region was decreased by FMN/CAL, and NOS2 expression in tumor tissues and cells were also decreased." (PMID 37298670, 2023). "ARG-1 and NOS2 use L-arginine as a substrate and deplete L-arginine from the tumor microenvironment, producing nitric oxide and ROS, mediating T cell suppression." (PMID 35873573, 2022). "IL‐34 blocking abrogated the TAM infiltration in murine HM‐1 and CT26 tumor model and increased the infiltration of NOS2‐positive M1‐like TAMs,44 and this suggested IL‐34 was also involved in M2‐polarization of TAMs." (PMID 35132816, 2022). "As a marker used to define M1 macrophages, the higher abundance of NOS2 in tumor islets is often related to better prognosis." (PMID 35493303, 2022). "The expression of CD68 and NOS2 was stronger in tumor stroma than in normal tissue but weaker in tumor parenchyma than in normal tissue." (PMID 35646079, 2022). "Further, qPCR analysis of normal appearing colonic mucosa and tumor samples showed that the expression of β-catenin and NF-κB downstream gene targets (Ptges2, Nos2, and Ccnd1) were greater in 28Si exposed mice relative to control and γ radiation groups." (PMID 36584137, 2022). "The expression of inducible nitric oxide synthase (iNOS; NOS2) and derived NO in various cancers was reported to exert pro- and anti-tumorigenic effects depending on the levels of expression and the tumor types." (PMID 35740092, 2022). "PD-L1 and NOS2 expression in both tumor and DCs were induced by the sustained IFN-β transcription, and NOS2 inhibition maintained long-term control of tumors with anti-PD-1 treatment." (PMID 35292881, 2022). "Drug administration subverted the phenotype of tumor-infiltrating CD11b+ Ly6Chi Ly6G− myeloid cells, favoring NOS2/ROS secretion and expression of pro-inflammatory genes characteristic of M1 polarization." (PMID 34930302, 2021). "Tumor expression of NOS2 was significantly inversely correlated (ρ = −0.47, p = 0.014) with TNM stage (I-II-III-IV)." (PMID 34439753, 2021). "Tumor expression of NOS2 was decreased in patients with lymph node (by 6.3-fold) and distant metastasis (by 19.7-fold) compared to those without metastases." (PMID 34439753, 2021). "We observed in disks, spheroids, and tumor tissue that different 4T1 cells expressed high levels of either NOS2 or COX2 and that high NOS2-expressing cells tended to be clustered together under hypoxic conditions." (PMID 33859337, 2021). "Nitric oxide synthase 2 (NOS2) was mainly expressed in liver and was found to provide crucial signals for angiogenesis in the tumor microenvironment." (PMID 34176789, 2021).